INS (insulin)
Diseases named in the same sentence as INS in open-access papers (continued):
Sharing a sentence is not in itself a finding about the gene and the disease.
Insulin resistance (continued). "Whole-body knockout of APPL1 impairs adiponectin signaling and results in insulin resistance in major insulin target tissues." (PMID 26993044, 2016). "This study documents a novel prospective on functional adipogenesis that appears to play a central role in providing adipose tissue insulin sensitivity and functionality and in preventing the development of insulin resistance and type II diabetes." (PMID 26904104, 2016). "Systemic chemerin administration results in whole-body insulin resistance and differentially regulates insulin sensitivity in different cell types, such as adipocytes and muscle cells." (PMID 26873079, 2016). "Both glucose and insulin can hyperactivate mTOR, creating a negative feedback loop via S6 kinase to degrade insulin receptor substrate 1/2, impairing insulin signaling, and leading to insulin resistance." (PMID 27922820, 2016). "F-FOPS mice experienced significant improvements in both fasting glucose and insulin levels, which were accompanied by a 79% reduction in the index of insulin resistance compared with HF-fed mice." (PMID 26731528, 2016). "The blunted ratios of increased MYO-INS to decreased DCI in urine have been indicated as marker of insulin resistance in human subjects." (PMID 27688754, 2016). "Insulin resistance and increased insulin secretion has been found early before development of diabetes." (PMID 27270732, 2016). "This novel mechanism of action means SGLT2 inhibitors function independently of insulin levels, pancreatic function and degree of insulin resistance." (PMID 27422625, 2016). "MYO-INS has also been reported to significantly decrease hyperandrogenism (p < 0.001) and insulin resistance (p < 0.001) in women with PCOS." (PMID 27688754, 2016). "Insulin resistance refers to a decreased capacity of target cells to respond to normal levels of circulating insulin due to impairment of one or more signaling pathways." (PMID 27274905, 2016). "Glucocorticoids exert well-characterized effects on metabolism, including permissive effects on glucagon and inhibition of insulin action that result in impaired peripheral glucose uptake and insulin resistance." (PMID 27037194, 2016). "While whole body insulin sensitivity was not different between WT and GPRKO mice, WT female mice fed a HFD had higher insulin and leptin levels than those in GPRKO female mice (p < 0.05), which are typically associated with obesity and insulin resistance." (PMID 27698362, 2016). "After 4 weeks of CR, SL mice were able to regulate their glycaemia after the injection of glucose or insulin, while glucose intolerance and insulin resistance persisted in SLAL mice." (PMID 27465434, 2016). "In conclusion, AnK-treated mice had not only lowered blood glucose and insulin, but also decreased triglyceride, total cholesterol levels, and finally ameliorated insulin resistance." (PMID 27242912, 2016). "For instance, increased insulin resistance results in both elevated serum glucose and insulin, both of which can stimulate the IGF and other proliferative pathways, leading to increased cancer growth and resiliency from damage induced by RT." (PMID 26977321, 2016). "In contrast, metformin, an insulin sensitizer, not only reduces levels of circulating glucose and insulin but also has potential protective effects on carcinogenesis in patients with insulin resistance and hyperinsulinemia." (PMID 27642100, 2016). "Ipragliflozin reduced the levels of fasting plasma glucose and insulin, and improved insulin resistance significantly in SGLT2I mice." (PMID 26731267, 2016). "It has been predominantly attributed to a combination of reduced insulin secretory capacity and insulin resistance." (PMID 27872738, 2016). "Clinical trials in children and adolescents with insulin resistance and obesity also rendered favorable outcomes, with general improvements in fasting glucose, insulin, triglycerides, BMI, HOMA-IR, TNFa, leptin, adiponectin, and blood pressure." (PMID 27258299, 2016).
Insulin resistance (continued). "Fasting insulin levels are the major indicator of insulin resistance and are increased by obesity and decreased with higher degree of physical activity." (PMID 27275336, 2016). "During insulin resistance, there is a failure of cells to metabolize glucose, which consequently triggers an increase of insulin level." (PMID 26881095, 2016). "When tissue, skeletal, and hepatic glucose uptake decreases, blood glucose level and plasma insulin increase, and result in insulin resistance." (PMID 27147943, 2016). "The HOMA2‐IR model was derived empirically from human insulin–glucose clamp data, but remains a useful surrogate measure of insulin resistance in mice." (PMID 26463117, 2016). "Considerable experimental and clinical data support this view: insulin signaling and insulin resistance affect the physiopathology of tau." (PMID 26858121, 2016). "We monitored the impact of HUA on insulin resistance, insulin signaling and IR, phospho-IRS1 (Ser307) and phospho-Akt levels in myocardial tissue of an acute hyperuricemia mouse model established by potassium oxonate treatment." (PMID 26836389, 2016). "Primary prevention programs should focus on overweight and obese adolescents, particularly girls, in view of the significantly higher fasting insulin and insulin resistance in girls as documented." (PMID 27824069, 2016). "The aim of the present study was to assess to what extent elevation of MCP-1 production in muscle and elevated MCP-1 levels in plasma interfere with insulin signalling in skeletal muscle and promote insulin resistance." (PMID 26661101, 2016). "Uric acid was found to directly inhibit insulin signaling and induce insulin resistance, which is considered to be an essential mechanism of NAFLD." (PMID 27382573, 2016). "Collectively, these studies suggest a pathological role of redox induced lipid peroxidation and SAPK signaling in aberrant insulin signaling and subsequent insulin resistance." (PMID 27695421, 2016). "The activities of insulin signaling pathway were measured by phosphorylation level of insulin receptor as a parameter of insulin resistance." (PMID 28053990, 2016). "Based on the intermediates observed, insulin resistance in T1D is characterized by an insulin-desensitizing intramyocellular fatty acid metabolite profile that is ameliorated with exercise training." (PMID 27197730, 2016). "The principal objective of present study was based on the fact that defects in the insulin signaling pathway leads to T2D and insulin resistance is crucial stage on the onset of this disease." (PMID 27602317, 2016). "Women who reported fewer than 6 hours of sleep had increased fasting insulin levels (difference in means = 2.13; 95% CI, 0.27 to 3.99 mU/L) and higher odds of insulin resistance (OR = 2.58; CI, 1.16 to 5.76)." (PMID 27870902, 2016). "This study also indicates that horses with insulin resistance, in similarity to humans, have a altered response to the cardiovascular effects of insulin." (PMID 27766986, 2016). "In accordance with BCH-induced restoration of insulin signals, stress/inflammation signals that play key roles in the induction of insulin resistance in HF/HFr-fed mouse liver were significantly down-regulated by the BCH treatment." (PMID 27874078, 2016). "TT treatment in mice not only lowered blood glucose and insulin levels, but also reduced triglycerides and total cholesterol levels; and finally ameliorated insulin resistance." (PMID 27271603, 2016). "Nonetheless, high-fat diet-induced elevations in fasting blood glucose and insulin as well as homeostasis model assessment of insulin resistance (HOMA-IR) were effectively suppressed by yellow tea." (PMID 27531374, 2016). "The level of GK expression is primarily controlled by insulin and studies have shown that high fat feeding will induce liver insulin resistance with a concomitant reduction in GK expression and activity." (PMID 26790104, 2016).
Insulin resistance (continued). "SEM analysis about the relationships among serum irisin, adiposity, glucose, insulin and insulin resistance shows that a one pathway model fits well (χ2 = 44.09, p < 0.001; CFI–0.994; TLI =0.986; and RMSEA = 0.067)." (PMID 27473122, 2016). "When Asians increase insulin resistance, they exhibit normal insulin levels or hypoinsulinemia and easily progress from glucose intolerance to type 2 diabetes." (PMID 26978400, 2016). "One of the most important contributing factors to CVD is insulin resistance, which refers to a decreased sensitivity and responsiveness to the metabolic actions of insulin." (PMID 27633375, 2016). "Insulin resistance (IR) and impaired insulin secretion contribute to type 2 diabetes and cardiovascular disease." (PMID 27768686, 2016). "Nevertheless, metformin has been reported to improve insulin resistance and reduce the dose of exogenous insulin needed to control hyperglycemia in patient with anti-insulin receptor antibodies." (PMID 27142369, 2016). "T2D is a chronic disease characterized by hyperglycemia, insulin resistance, defective insulin secretion and islet of Langerhans remodeling." (PMID 27473212, 2016). "Accompanying an impaired transendothelial access of insulin to the hepatocytes, there were significant systemic changes including reduced hepatic insulin uptake and clearance, increased insulin levels and insulin resistance." (PMID 27095270, 2016). "The action of insulin in liver is to suppress hepatic glucose production and hepatic insulin resistance, which is characterized by a decrease in the ability of insulin to suppress hepatic gluconeogenesis." (PMID 27220352, 2016). "When gefitinib, an EGFR tyrosine kinase inhibitor, was treated in high-fat diet fed Mig-6d/d mice, fasting insulin concentration, insulin resistance, and hypercholesterolemia were ameliorated." (PMID 28053990, 2016). "Plasma leptin levels correlated with plasma fasting insulin levels, pre-pregnant body mass index, homeostasis model assessment-insulin resistance and quantitative insulin sensitivity check index both in GDM and NGT group (P < 0.05)." (PMID 27034205, 2016). "It is possible that sFRP2-mediated adipose tissue expansion and insulin secretion is a potential compensatory mechanism in the setting of visceral adiposity and insulin resistance." (PMID 27685706, 2016). "These variations of improvement in insulin resistance and insulin levels can be ascribed to the effects of metformin or pioglitazone." (PMID 28331909, 2016). "Of note, the relative insulin resistance observed is in most cases due to increased insulin levels, whereas serum glucose remains normal." (PMID 27148273, 2016). "Although OLETF rats acquire insulin resistance, at 20–25 weeks of age, it is compensated by increased insulin secretion, which results in higher AUC180." (PMID 27483133, 2016). "AMPK is also lower in insulin resistant, obese individuals (homeostatic model of insulin resistance (HOMA-IR) > 2.3), compared to BMI-matched counterparts." (PMID 27128935, 2016). "Studies using animal models have also shown that the increased levels of insulin that result from insulin resistance compounded by exogenous insulin administration lead to an increased level of vulnerability to chemically induced carcinogenesis." (PMID 26967162, 2016). "Increased intracellular FFAs content strongly affects insulin signaling pathway and contributes to insulin resistance condition." (PMID 27471733, 2016). "Overall, our data argue against MCP-1 promoting insulin resistance in skeletal muscle and raise questions about the impact of inflammation on insulin sensitivity in muscle." (PMID 26661101, 2016). "GC-induced hepatic insulin resistance results in impaired suppression of hepatic glucose production by insulin." (PMID 27929385, 2016). "Both ob/ob and lipodystrophic mice develop severe insulin resistance due to impaired insulin signalling failing to suppress gluconeogenesis and hepatic steatosis." (PMID 25740151, 2016).
Insulin resistance (continued). "These miRNAs were also correlated with indices of insulin secretion, insulin resistance, and β-cell function in general (AUC-Insulin, AUC-C-peptide, HOMA-B, HOMA-IR, MATSUDA, QUICKI, ISSI2) in the subset of subjects who were not treated with insulin." (PMID 27558530, 2016). "At the onset of T2DM, there is a compensatory attempt of the beta cells to release more insulin to defeat insulin resistance." (PMID 27496100, 2016). "Third, CCR5 and CCL5 regulatory effects on insulin signaling in hypothalamus contribute to peripheral insulin resistance and glucose intolerance." (PMID 27898058, 2016). "The aCD3 + OFS group had higher insulin sensitivity as measured by homeostasis model assessment of insulin resistance (HOMA-IR) and in response to intraperitoneal injection of insulin during an insulin tolerance test." (PMID 27874076, 2016). "Women with PCOS have various degrees of insulin resistance and disturbances in insulin secretion and function have an important role in pathophysiology of this disorder." (PMID 27351028, 2016). "Insulin sensitivity is an important measure of metabolic health, with lower sensitivity (insulin resistance) comprising a core component of the metabolic syndrome." (PMID 27876008, 2016). "Dysregulated insulin signaling is an integral factor in the development of insulin resistance and type 2 DM." (PMID 28050570, 2016). "Type II diabetes is partly a result of lipid deregulation and development of insulin resistance, leading to impaired insulin-dependent glucose uptake in the skeletal muscle." (PMID 28005939, 2016). "Peripheral insulin resistance represents a decrease in insulin-dependent glucose transport in insulin responsive tissues, which can be the product of defects at both the insulin receptor and/or postreceptor signaling." (PMID 27274997, 2016). "T2D is characterized by insulin resistance, which leads to hyperglycemia, owing at least in part to the impaired ability of insulin to suppress expression or activity of gluconeogenic enzymes." (PMID 27622707, 2016). "Mc4rmut mice develop a late-onset hyperglycemia and normal basal blood glucose levels but increased insulin levels and hepatic insulin resistance have been reported." (PMID 28030540, 2016). "Type 1 DM and type 2 DM patients of East Asian origin share the same feature, with an insulin secretory defect that is more dominant, although insulin resistance is also involved in the development of the disease." (PMID 27275953, 2016). "The reduction in AD found, on average, in patients with PCOS compared with controls was evident in those with relatively normal insulin AUC (<100 000 pmol min/L) but AD was increased in a subset of PCOS patients with marked insulin resistance." (PMID 26574952, 2016). "These abnormalities of glucose metabolism occur as a consequence of insulin resistance and impaired insulin secretion induced by GCs excess." (PMID 26901633, 2016). "It would have been potentially beneficial to correlate insulin levels with other parameters of insulin resistance to further corroborate our findings." (PMID 27599544, 2016). "Leucine, tryptophan, and valine levels exhibited positive correlations with insulin resistance (HOMA-IR) or insulin secretion (HOMA-β and II)." (PMID 26788116, 2016). "Hyperinsulinemia from endogenous hypersecretion of insulin is common in the early stages of type 2 diabetes as a ‘pathophysiological’ response to insulin resistance; it also occurs as a consequence of exogenous insulin therapy." (PMID 26060511, 2015). "The improvement of adiponectin level in the current study also reflected the effect of GLP-1 analogue add-on intensive insulin therapy in the cardiovascular protection in addition to reduced insulin resistance." (PMID 26607841, 2015). "Insulin resistance refers to the reduced response of glucose uptake to the stimulatory effect of insulin." (PMID 26253538, 2015).
Insulin resistance (continued). "Both strains also exhibited high insulin resistance, but C3H mice showed low basal and stimulated insulin secretion." (PMID 25946019, 2015). "Previous studies with children and adolescents have reported strong correlations between adiponectin and markers of insulin resistance, such as fasting serum insulin or homeostasis model assessment of insulin resistance (HOMA-IR)." (PMID 25904939, 2015). "Though adiponectin is expressed predominantly by adipose tissue, its plasma concentrations have been demonstrated to be negatively correlated with BMI, insulin resistance and insulin concentrations." (PMID 26030130, 2015). "Exposure of the liver to high levels of fructose leads to rapid stimulation of lipogenesis and triglyceride accumulation, which lead to reduced insulin sensitivity and hepatic insulin resistance/glucose intolerance." (PMID 26504474, 2015). "In NAFLD, the initial site appears to be in the periphery, followed by or resulting in hepatic steatosis, which exacerbates hepatic insulin resistance and thus the degree of overall insulin resistance." (PMID 25892856, 2015). "The levels of plasma glucose, insulin and a measure of insulin resistance (HOMA-IR), were determined." (PMID 26694027, 2015). "Insulin resistance decreased while insulin sensitivity increased, and overall, glucose tolerance improved by 33%, compared to only a 9.5% increase in those receiving fresh non-fermented control." (PMID 25580813, 2015). "Insulin resistance is a multi-faceted disruption of the communication between insulin and the interior of a target cell." (PMID 26415887, 2015). "Across the WHO OGTT subgroups in Caucasian families, we observed a clear trend from normal insulin sensitivity to insulin resistance, while the DI decreased." (PMID 24791963, 2015). "First, we observed that myocardial insulin resistance occurred as early as 1 wk following surgically-induced MI in rats, while systemic insulin sensitivity and glucose tolerance remained normal." (PMID 26659007, 2015). "E. Tubbs recently showed that such alterations in hepatocytes dysregulate insulin signalling and promotes insulin resistance." (PMID 26035647, 2015). "It has also been reported that increased serum resistin levels in obese patients with insulin resistance and resistin impair glucose homeostasis and insulin action in mice." (PMID 26681840, 2015). "When analyzed using IHTG as an independent variable, hepatic insulin resistance in fatty liver was due to blunted sensitivity to insulin in suppressing fluxes through all pathways of glucose production rather than persistent flux through a specific pathway." (PMID 25250633, 2015). "Abnormal insulin action in the liver results in insulin resistance characterized by an impaired ability of insulin to inhibit glucose output, leading to gluconeogenesis and hyperglycemia." (PMID 26507490, 2015). "A recent review has outlined studies determining the effect of MUFA on insulin resistance, demonstrating improved insulin sensitivity and glucose regulation following MUFA-rich diets in both healthy and diabetic individuals." (PMID 26404365, 2015). "Seventeen randomized controlled trials were included, in which 17 fasting blood glucose (n = 1105), 11 fasting plasma insulin (n = 788), 8 homeostasis model assessment of insulin resistance (n = 635) comparisons were reported." (PMID 26161741, 2015). "Overweight PWS patients had less insulin resistance and greater insulin sensitivity than was found in BMI-matched controls (HOMA: 0.86±0.46 vs 2.04±1.26, p<0.001; QUICKI: 0.41±0.04 vs0.35±0.02, p<0.001)." (PMID 26334732, 2015). "Many studies have tried to demonstrate the beneficial effect of adding insulin sensitiser agents to peginterferon and ribavirin in order to enhance viral clearance in genotype 1 chronic hepatitis C with insulin resistance." (PMID 25821463, 2015).